FCGBP (Fc gamma binding protein)
Description:
May be involved in the maintenance of the mucosal structure as a gel-like component of the mucosa.
Synonyms: FcgammaBP; FC(GAMMA)BP
Gene: Protein-coding gene on chromosome 19 (39,863,323 to 39,934,626, reverse strand). Ensembl gene ENSG00000275395.
Subcellular location: Secreted
Subcellular location (Human Protein Atlas): Plasma membrane; Cytokinetic bridge; Golgi apparatus; Predicted to be secreted
Genetic constraint (gnomAD): Loss-of-function variants: 132 observed, 239.04 expected, observed/expected ratio (o/e) 0.55, 90% interval 0.48 to 0.64. The synonymous counts are far from expectation, so gnomAD's model fits this gene poorly and the ratio says little. Missense variants: 2,630 observed, 3,768.6 expected, observed/expected ratio (o/e) 0.7, 90% interval 0.68 to 0.72. Synonymous variants: 1,189 observed, 1,561.2 expected, observed/expected ratio (o/e) 0.76, 90% interval 0.73 to 0.8.
Homologues: Orthologues: tropical clawed frog XB5897453 (27% identical), zebrafish si:dkey-65b12.6 (25% identical), chimpanzee FCGBP (16% identical). Paralogues in human: ZAN (16% identical), TECTA (14% identical), MUC5B (12% identical), MUC5AC (12% identical), OTOG (11% identical), VWF (11% identical), OTOGL (10% identical), KCP (8% identical), MUC19 (8% identical), MUC6 (8% identical), MUC2 (7% identical), CRIM1 (5% identical), and 7 more.
Diseases named in the same sentence as FCGBP in open-access papers:
FCGBP is named in the same sentence as 88 diseases in open-access papers, as found by Europe PMC text mining. Sharing a sentence is not in itself a finding about the gene and the disease. The quoted sentences say what the papers report.
gallbladder cancer (13 papers, 2014 to 2023). "We further provided evidences that high FCGBP expression was associated with favorable prognosis, which was consistent with its effects in ovarian cancer, colorectal cancer, and gallbladder cancer." (PMID 35733916, 2022). "FCGBP expression is an independent indicator of disease progression, clinical biological behavior, and prognosis in patients with gallbladder cancer." (PMID 35936008, 2022). "Univariate Kaplan–Meier survival analysis shows that the expression of FCGBP correlates significantly with the mean survival time in patients with gallbladder cancer." (PMID 35936008, 2022). "FCGBP represents the most under-expressed gene in the TGF-β-induced gallbladder carcinoma-derived cells compared to a normal cell line, suggesting its role in TGFβ-induced EMT to drive metastatic behaviors." (PMID 35626334, 2022). "reported, decreased FCGBP in gallbladder carcinoma cell line (GBC-SD cells) suggests that FCGBP is an important marker for clinical biological behavior and progression." (PMID 35936008, 2022). "Many studies have confirmed that FCGBP plays an important role in various malignancies, including ovarian cancer, glioblastoma, colorectal cancer, gallbladder cancer, head and neck squamous cell carcinoma, prostate cancer, papillary thyroid carcinoma, and osteosarcoma." (PMID 36803544, 2023). "In addition, gallbladder cancer has low levels of FCGBP expression, and this protein is a critical regulator of the TGF-1-induced EMT progress." (PMID 35733916, 2022). "FCGBP is the most profoundly downregulated transcript during TGF-β-induced EMT in gallbladder cancer cells, suggesting that it may play an important role in this process." (PMID 35936008, 2022). "Low expression of FCGBP could be used as a crucial regulator of tumour growth factor 1 (TGF-1)-induced epithelial-mesenchymal transition in gallbladder cancer." (PMID 35109839, 2022). "According to the latest literature, study revealed that FCGBP participates in the development of gastric neoplasm, and is also a key regulatory factor in the epithelial-mesenchymal transformation process of gallbladder cancer metastasis and prognosis." (PMID 34187591, 2021). "Overexpression of FCGBP has hazard ratio of 0.306 (95% CI: 0.136–0.686) for gallbladder cancer." (PMID 34442426, 2021). "FcGBP was also indicated as a prognosis marker in gallbladder cancer." (PMID 33648461, 2021). "The participation of FCGBP in gastric tumorigenesis and progression was also revealed 32, and FCGBP is validated as a key regulator of the epithelial–mesenchymal transition process that contributed to the metastasis and prognosis of gallbladder cancer." (PMID 30868060, 2019). "So measurement of NT5E and FcGBP expression could be used as a tool for early detection of gallbladder cancer in benign lesions as well as population screening." (PMID 24310606, 2014). "After reference review, we thought that NT5E and FcGBP might play important roles in the invasion and metastasis of gallbladder cancer with TGF-β1 induced EMT." (PMID 24310606, 2014). "The data from the current study indicate that differential NT5E and FcGBP expressions could be further evaluated as biomarkers for predicting survival of patients with gallbladder cancer and that NT5E and FcGBP could be promising targets in the control of gallbladder cancer progression." (PMID 24310606, 2014).
colorectal cancer (11 papers, 2012 to 2024). A primary or metastatic malignant neoplasm that affects the colon or rectum. "The pathogenic roles of FCGBP in malignancy were firstly reported for its implication in ulcerative colitis, a condition that predisposes to colorectal cancer development." (PMID 35626334, 2022). "FCGBP is significantly correlated with patient survival and prognosis across various cancers, including colorectal cancer, lung cancer, esophageal cancer, and glioma." (PMID 39484038, 2024). "Significantly low expression of FCGBP has been observed in intestinal inflammation and tumors, such as ulcerative colitis, colorectal adenoma, and colorectal cancer." (PMID 35047393, 2021). "Moreover, FCGBP expression levels were reported to positively correlate with the survival rate in colorectal cancer, including primary lesions and liver metastases." (PMID 36803544, 2023). "Moreover, the FCGBP protein levels in colorectal cancer, were lower in metastatic tissues than in the paired primary tumors, and validated as an independent prognostic factor for metastatic colon cancer." (PMID 35626334, 2022). "In contrast, high expression of FCGBP significantly decreases the OS of colorectal cancer patients." (PMID 35109839, 2022). "In contrast, FCGBP is highly expressed in colorectal cancer, particularly in metastatic tissues." (PMID 33686968, 2021). "Moreover, increased expression of FCGBP significantly decreases the overall survival (OS) of colorectal cancer patients." (PMID 33686968, 2021). "To date, there is no reported connection between FCGBP and IBD; however, reduced FCGBP has been associated with the onset and progression of colorectal cancer, which can develop secondary to chronic gut inflammation." (PMID 35239459, 2022).
glioma (8 papers, 2021 to 2026). A benign or malignant brain and spinal cord tumor that arises from glial cells (astrocytes, oligodendrocytes, ependymal cells). "FCGBP has been shown to be upregulated in glioma tissues and to be associated with increased immune cell invasion." (PMID 38732562, 2024). "For example, FCGBP is associated with immune infiltration in glioma." (PMID 38396964, 2024). "Furthermore, FCGBP expression was positively associated with multiple immune cells infiltrates as well as the expression levels of multiple immune markers in glioma." (PMID 35047393, 2021). "While diminished expression levels of FCGBP have been noted in gallbladder and prostate cancers, contrasting observations reveal elevated FCGBP expression in glioma, hepatocellular carcinoma, and ovarian cancer." (PMID 38709264, 2024). "An mRNA vaccine designed to target FCGBP has shown some promise in the treatment of low-grade gliomas." (PMID 35936008, 2022). "High FCGBP protein abundance contributes to increased recruitment of immune cells in low-grade gliomas in these nervous system malignancies." (PMID 35936008, 2022). "Then, all CGGA database analysis found that FCGBP was also significantly up-regulated in glioma, and positively correlated with the grade of glioma." (PMID 35047393, 2021). "In the present study, we aimed to identify the expression of FCGBP and its correlation with prognosis, and possible signaling pathway in glioma." (PMID 35047393, 2021). "In order to study the potential function of FCGBP in glioma, we used the LinkedOmics database to explore related molecules of FCGBP." (PMID 35047393, 2021). "The novelty of this study is that we firstly found that FCGBP has a poor prognostic in glioma, and we also explored the possible mechanism of FCGBP in glioma." (PMID 35047393, 2021). "Especially in the central nervous system (CNS), the expression of FCGBP in five glioma datasets were all up-regulated." (PMID 35047393, 2021). "Survival curve analysis was verified via three independent CGGA cohorts, and revealed that high expression of FCGBP had a significant poor prognosis in glioma." (PMID 35047393, 2021). "Through the TCGA and CGGA databases, we first found that FCGBP was highly expressed in glioma tissues and had a significant positive correlation with the grade of glioma." (PMID 35047393, 2021). "Further univariate and multivariate Cox regression analysis showed that FCGBP can be significantly negatively correlated with the prognosis of glioma patients in TCGA and CGGA." (PMID 35047393, 2021). "Firstly, FCGBP was highly expressed in glioma and correlated with a worse prognosis." (PMID 35047393, 2021). "To verify the upregulation of FCGBP in gliomas, we performed IHC analysis using glioma samples." (PMID 35047393, 2021). "We confirmed the correlation between FCGBP and immune infiltration of glioma, and proposed that FCGBP may act a novel immunotherapy biomarker." (PMID 35047393, 2021). "We found that PDL1 and FCGBP were synchronously upregulated in glioma tissues." (PMID 35047393, 2021). "However, the biological role of FCGBP has remained unclear in glioma." (PMID 35047393, 2021). "In the BrM/Glioma group, 8 DEPs (PRL, SNCA, MACF1, ACAT2, VWF, GSN, FCGBP, and F10) were selected for ROC curve analysis based on a logistic regression model." (PMID 39716938, 2025). "The results showed that the transcription level of FCGBP in GBM and low-grade glioma (LGG) tissues was significantly higher than normal tissues." (PMID 35047393, 2021). "FCGBP is not detectable in normal brain tissue, but it is expressed in different grades of gliomas, especially high-grade gliomas." (PMID 35047393, 2021). "Finally, immunohistochemistry (IHC) assays were conducted to explore the expression of FCGBP, PD-L1, CCL2 and CD8 in glioma and correlations between them." (PMID 35047393, 2021). "However, there is no molecular study of FCGBP in glioma cells, further demonstration is needed." (PMID 35047393, 2021).
ovarian carcinoma (8 papers, 2021 to 2024). A malignant neoplasm originating from the surface ovarian epithelium. "FCGBP was highly expressed and associated with poorer overall survival (p = 0.00051) and disease-specific survival (p = 0.0012) in ovarian cancer and other tumors." (PMID 33686968, 2021). "Notably, FCGBP expression has demonstrated associations with chemotherapy responses in patients with ovarian cancer, suggesting a modulatory role in the efficacy of contemporary anticancer modalities." (PMID 38709264, 2024). "For instance, ovarian cancer patients with high levels of FCGBP had a lower overall survival and disease-specific survival than those with lower levels of the protein." (PMID 35733916, 2022). "For example, in ovarian cancer, FCGBP protein expression correlates with the expression of the macrophage marker CD163, Mrc1, and TGFβ1." (PMID 35936008, 2022). "Our results suggest potential functional role of FCGBP in ovarian cancer, thereby highlighting a mechanistic basis whereby FCGBP influences M2 macrophage polarization in the tumor microenvironment." (PMID 33686968, 2021). "Our study suggests that FCGBP contributes to M2 macrophage polarization by acting as an oncogene in ovarian cancer." (PMID 33686968, 2021). "FCGBP expression was analyzed using The Cancer Genome Atlas (TCGA) pan-cancer data, and the ovarian cancer expression profile was analyzed using the Gene Expression Omnibus database." (PMID 33686968, 2021). "Previous studies have found that ovarian cancer with high FCGBP expression had a worse prognosis, which was consistent with our results." (PMID 35047393, 2021). "FCGBP was highly positively correlated with immunosuppressive genes in most tumors, including ovarian cancer." (PMID 33686968, 2021). "The results confirmed that FCGBP was overexpressed in ovarian cancer tissues compared with normal ovarian tissues." (PMID 33686968, 2021). "We further assessed the immune cell infiltration score of TCGA ovarian cancer and found that the M2 macrophage infiltration level was high, while that of M1 macrophages was low in the high-FCGBP expression group." (PMID 33686968, 2021). "FCGBP has been found to be downregulated in many cancers including ovarian cancer." (PMID 39149564, 2024). "This suggests that FCGBP is also involved in regulating the infiltration of immune cells in the tumor microenvironment of ovarian cancer, where it may be a valuable marker for prognostic evaluation." (PMID 35936008, 2022). "Moreover, FCGBP also contributes to M2 macrophage polarization by acting as an oncogene in ovarian cancer." (PMID 34187591, 2021). "In summary, FCGBP likely plays an important role in immune cell infiltration and may represent a valuable prognostic biomarker for ovarian cancer." (PMID 33686968, 2021). "By analyzing the relationship between FCGBP and immune cell infiltration, we found that the M2 macrophage infiltration level was significantly higher in the high FCGBP expression group; in this group, the M1 macrophage infiltration level was lower in ovarian cancer." (PMID 33686968, 2021). "In addition, as a tumor promotor in ovarian cancer, FCGBP may contribute to the polarization of macrophages into M2 cells." (PMID 35733916, 2022). "However, the correlation between FCGBP and immune cell infiltration in ovarian cancer remains unclear." (PMID 33686968, 2021). "In addition, FCGBP was highly expressed in ovarian cancer in the GSE12470 and GSE40595 datasets." (PMID 33686968, 2021). "Recently, a paper also showed that FCGBP is high-expressed in ovarian cancer in GSE12470 and GSE40595, and high-expressed FCGBP is significantly correlated with immune-related gene sets." (PMID 34187591, 2021). "However, the role of FCGBP in ovarian cancer remains unknown." (PMID 33686968, 2021). "High FCGBP expression was correlated with poorer OS and disease-specific survival (DSS) of ovarian cancer patients." (PMID 33686968, 2021).
ovarian carcinoma (continued). "Furthermore, FCGBP, MAP4K2, IL12A, and HSPA2 showed similar expression levels in ovarian cancer compared to normal tissues." (PMID 39149564, 2024). "Meanwhile, KEGG analysis indicated that FCGBP was involved in the chemokine signaling pathway, RAP1 signaling pathway, human T cell leukemia virus 1 infection, and B cell receptor signaling pathway in ovarian cancer." (PMID 33686968, 2021).
autoimmune disease (7 papers, 2014 to 2025). A disorder resulting from loss of function or tissue destruction of an organ or multiple organs, arising from humoral or cellular immune responses of the individual to their own tissue constituents. "FCGBP has been regarded as a constituent of human saliva and high expressed in salivary glands and several autoimmune diseases." (PMID 34723755, 2021). "The function of FCGBP is poorly understood and has previously been reported as elevated in serum of patients with autoimmune disease." (PMID 34232570, 2021). "FCGBP is a component of the mucus layer coating of the intestinal tract, and expression is higher in several autoimmune diseases." (PMID 24988487, 2014). "First, considering blood concentration of FCGBP is elevated in autoimmune diseases, its assessment may be correlated with intestinal expression in asthmatics." (PMID 34332619, 2021). "Therefore, it has been proved higher level of FCGBP in the blood stream of patients with autoimmune diseases, suggesting an increased generation of FCGBP in goblet cells and its secretion into the circulation by an unknown mechanism." (PMID 36371440, 2022). "Eleven proteins (increased: ATP5B, CALML5, COLEC11, FCGBP, PLEK, PLXND1; decreased: APOB, ATP8B1, FAM20C, LOXL3, TIMD4) were significantly altered in bvFTD with autoimmune disease compared to those without autoimmune disease." (PMID 34539672, 2021).
colon cancer (7 papers, 2011 to 2022). "Some researchers have showed that the protein and mRNA expression levels of FCGBP decrease with the progression of the disease in the primary tissues and liver metastases of colon cancer." (PMID 35936008, 2022). "Meanwhile, in osteosarcoma and colon cancer, FCGBP is downregulated in tumor tissues compared with normal tissues, as well as in metastatic tissues compared with non-metastatic tissues." (PMID 33686968, 2021). "RELN and ALDH1A1 are expressed in prostate cancer, ENG, SI, FCGBP and PTPRT are associated with colonic tumors." (PMID 21533145, 2011). "Similarly, the expression of FCGBP is downregulated in colon cancer than that of surrounding normal tissues." (PMID 35936008, 2022). "Because FCGBP and MUC2 have highly similar domains, it is tempting to speculate that FCGBP plays a role in promoting the invasion and metastasis of colon cancer." (PMID 35936008, 2022). "FcGBP gene expression is significantly decreased in colon cancer carcinogenesis." (PMID 29156811, 2017). "The curves present survival data for the two groups of colon cancer patients based on gene expression level (high or low) of SPINK4, RETNLB, ASRGL1, CLCA1, and FCGBP (rows)." (PMID 31337362, 2019).
osteosarcoma (6 papers, 2019 to 2025). A usually aggressive malignant bone-forming mesenchymal neoplasm, predominantly affecting adolescents and young adults. "FCGBP, namely Fc gamma binding protein, was identified as being associated with osteosarcoma metastasis." (PMID 39428571, 2024). "A combination of eight genes (RAB1,CLEC3B,FCGBP,RNASE3,MDL1,ALOX5AP,VMO1 and ALPK3) were identified as being associated with osteosarcoma metastasis." (PMID 30868060, 2019). "Additionally, the active ingredients of HCSI inhibit tumor progression by enhancing FOXO1-mediated transcription of FCGBP in osteosarcoma." (PMID 40764575, 2025).
prostate carcinoma (6 papers, 2011 to 2024). A carcinoma that arises from epithelial cells of the prostate gland. "Down-regulation of Fc fragment of IgG binding protein (FCGBP) has been associated with decreased overall survival in gallbladder adenocarcinoma and with progression of prostate cancer in Transgenic adenocarcinoma Mouse Prostate (TRAMP)." (PMID 31337362, 2019). "FCGBP expression is reduced in human prostate cancers and the transgenic adenocarcinoma of mouse prostate cancer (TRMAP) disease model." (PMID 35936008, 2022).